PWP1 (PWP1 homolog, endonuclein)
Description:
Chromatin-associated factor that regulates transcription. Regulates Pol I-mediated rRNA biogenesis and, probably, Pol III-mediated transcription. Regulates the epigenetic status of rDNA.
Synonyms: IEF-SSP-9502; NCLB
Tractability: PROTAC: ubiquitination databases record sites on it; its protein half-life has been measured.
Gene: Protein-coding gene on chromosome 12 (107,685,766 to 107,713,462, forward strand). Ensembl gene ENSG00000136045.
Subcellular location: Nucleus; Nucleus, nucleolus; Chromosome
Subcellular location (Human Protein Atlas): Nucleoli rim; Golgi apparatus
Gene Ontology:
Molecular function: histone H4K20me3 reader activity
Biological process: positive regulation of transcription of nucleolar large rRNA by RNA polymerase I; DNA-templated transcription; chromatin organization; regulation of DNA-templated transcription; rRNA processing
Cellular component: chromosome; nucleolus; nucleus
Genetic constraint (gnomAD): Loss-of-function variants: 39 observed, 61.13 expected, observed/expected ratio (o/e) 0.64, 90% interval 0.49 to 0.83. The upper end of that interval is the gene's LOEUF score, 0.83, which puts it in group 3 of 6, group 1 being the genes least tolerant of losing a copy. Missense variants: 489 observed, 569.56 expected, observed/expected ratio (o/e) 0.86, 90% interval 0.8 to 0.93. Synonymous variants: 203 observed, 197.14 expected, observed/expected ratio (o/e) 1.03, 90% interval 0.92 to 1.16.
Homologues: Orthologues: chimpanzee PWP1 (100% identical), macaque PWP1 (99% identical), dog PWP1 (99% identical), pig PWP1 (97% identical), rabbit PWP1 (96% identical), guinea pig PWP1 (93% identical), mouse Pwp1 (90% identical), rat Pwp1 (89% identical), tropical clawed frog pwp1 (71% identical), zebrafish pwp1 (68% identical), Drosophila melanogaster nclb (34% identical), Caenorhabditis elegans Y32H12A.8 (34% identical).
Diseases named in the same sentence as PWP1 in open-access papers:
PWP1 is named in the same sentence as 13 diseases in open-access papers, as found by Europe PMC text mining. Sharing a sentence is not in itself a finding about the gene and the disease. The quoted sentences say what the papers report.
osteosarcoma (2 papers, 2019 to 2025). A usually aggressive malignant bone-forming mesenchymal neoplasm, predominantly affecting adolescents and young adults. "To determine whether PWP1 regulated telomere length/structure in human cells, we performed PWP1 knockdown in human osteosarcoma cells, MG63 and U2OS, using an shRNA targeting PWP1 (shPWP1)." (PMID 31754456, 2019).
prostate carcinoma (2 papers, 2020 to 2025). A carcinoma that arises from epithelial cells of the prostate gland. "The inferred subset GRN from the PC3 prostate cancer cell line suggests several genes as suppressors of SDHB, such as PNKB, PWP1, PNP, HADH, HTATSF1, and BAZ1B, among which PWP1, HTATSF1, and BAZ1B are transcription regulators." (PMID 33168813, 2020).
dyskeratosis congenita (1 paper, 2019). Dyskeratosis congenita (DC) is a rare ectodermal dysplasia that often presents with the classic triad of nail dysplasia, skin pigmentary changes, and oral leukoplakia associated with a high risk of bone marrow failure (BMF) and cancer. "Interestingly, ~15% of Pwp1+/− mice exhibited a congenital absence of facial hair similar to mouse models of Dyskeratosis Congenita with mutations in genes of telomerase or the shelterin component Tin235,36." (PMID 31754456, 2019).
pancreatic cancer (1 paper, 2004). "Among the genes we predicted to function in RNA processing and ribosome biogenesis was PWP1, which encodes a protein that includes WD40 repeats and which has previously been found to be up-regulated in pancreatic cancer tissue." (PMID 15588312, 2004).
cancer (3 papers, 2018 to 2025). A tumor composed of atypical neoplastic, often pleomorphic cells that invade other tissues. "As inhibition of ribosome biogenesis is an emerging strategy for cancer therapy, the role of PWP1 in the joint control of Pol I and Pol III makes PWP1 an appealing target." (PMID 30361412, 2018).
tumor (3 papers, 2018 to 2024). "Interestingly, human PWP1 expression is highly elevated in aggressive tumors and knockdown of PWP1 leads to inhibition of tumor cell proliferation." (PMID 30361412, 2018).
PWP1 also shares sentences with these, for which no sentence is quoted: breast carcinoma (1 paper); cervical carcinoma (1); gastric cancer (1); hepatocellular carcinoma (1); infection (1); non-small cell lung carcinoma (1); ovarian carcinoma (1).